CRP (C-reactive protein)
Diseases named in the same sentence as CRP in open-access papers (continued):
Sharing a sentence is not in itself a finding about the gene and the disease.
gestational diabetes (59 papers, 2015 to 2025). Carbohydrate intolerance first diagnosed during pregnancy. "In pregnancy, several studies show association of elevated CRP with gestational diabetes mellitus (GDM)." (PMID 41256167, 2025). "Disruption of this balance, especially during early pregnancy, can elevate CRP levels, which have been associated with an increased risk of gestational diabetes mellitus (GDM), preeclampsia, and preterm birth." (PMID 41256167, 2025). "One earlier randomized controlled trial found that supplementation with CLO was associated with a decrease in CRP in a cohort of women with gestational diabetes." (PMID 34183020, 2021). "Significantly increased leukocyte SFTPD mRNA levels were observed in hyperglycemic gestational diabetes mellitus (GDM) patients (P < 0.05) with a significant positive association with C-reactive protein." (PMID 32547959, 2020). "A RCT of supplementation of 200 μg/day of selenium for 6 weeks in 70 women with gestational diabetes found significant improvements in fasting glucose, serum insulin, C-reactive protein, and oxidative stress." (PMID 34071548, 2021). "Structured exercise regime helps in reducing values of glycosylated hemoglobin and C reactive protein in patients with gestational diabetes mellitus." (PMID 33235555, 2020). "FPG, 2hPG, HOMA-IR and hs-CRP and perinatal complications were investigated after cod-liver oil consumption, so as to explore dietary control for gestational diabetes." (PMID 31956660, 2019). "Thus, we evaluated the impact of individually-tailored motivationally-matched exercise intervention on CRP levels in an ethnically diverse sample of pregnant women at high risk for gestational diabetes mellitus (GDM)." (PMID 26104503, 2015). "In a meta-analysis of five RCTs that included women with gestational diabetes, probiotic supplementation led to a significant reduction in CRP (p < 0.0001), IL-6 (p = 0.0005), and malondialdehyde (MDA) (p < 0.00001), and an increase in NO (p = 0.003) and total antioxidant capacity (TAC) (p = 0.01)." (PMID 37764004, 2023). "Similarly, evidence from a recent cohort of pregnant women reported that caffeine intake reduced the risk for gestational diabetes mellitus (GDM) by decreasing blood glucose, C-reactive protein and C-peptide levels, and resulted in favorable lipid profiles." (PMID 36582446, 2023). "Interestingly it has previously been reported that women with gestational diabetes mellitus show elevated serum levels of CRP, IL-6 and TNF-α." (PMID 25806806, 2015). "In addition, adherence to the DASH diet was signally associated with a reduced risk of gestational diabetes mellitus (GDM), and the mechanism may involve reducing oxidative stress, increasing glutathione peroxidase activity and inhibiting chronic inflammation (reducing C-reactive protein levels)." (PMID 41229546, 2025). "Structured exercise regime helps in reducing values of HbA1c and CRP in patients with gestational diabetes mellitus after 20 weeks gestation till 36 weeks so it can be a part of multidisciplinary management of GDM." (PMID 33235555, 2020). "While CRP levels have been linked to gestational diabetes, we found no strong genetic connection between CRP and GDM." (PMID 41256167, 2025). "Vitamin D and probiotics (L. acidophilus, B. bifidum, L. reuteri, and L. fermentum) co-supplementation was also reported to reduce serum levels of inflammation and oxidative stress biomarkers (hs-CRP and MDA) in gestational diabetes patients." (PMID 37216180, 2023). "There was a statistically significant difference between Group 1 and the other three groups; specifically, pregnant women without gestational diabetes or other complications had the lowest CRP values." (PMID 40941639, 2025).
gestational diabetes (continued). "Adipocytes secrete pro-inflammatory cytokines such as TNF-α, IL-6, and CRP, which interfere with immunological tolerance during pregnancy, promote oxidative stress, and impair endothelial nitric oxide (NO) production—hallmarks of preeclampsia and gestational diabetes mellitus (GDM)." (PMID 40981180, 2025). "Furthermore, systemic inflammation during pregnancy, defined as elevated serum levels of C-reactive protein (CRP) and/or interlukin-6 (IL-6), may serve as a precursor to gestational diabetes mellitus (GDM)." (PMID 33552314, 2021). "On ordinal logistic regression, gestational diabetes mellitus, initial fraction of inspiration O2 value, invasive ventilation, acidosis, hypochloremia, C-reactive protein level, patent ductus arteriosus and Gram-negative respiratory culture were independent risk factors for BPD severity." (PMID 36357648, 2023). "In gestational diabetes patients receiving a simple exercise program without behavioral recommendations, POC testing was associated with a reduction in maternal postprandial glucose, A1C, CRP, triglycerides and maternal or neonatal complications, but not in fasting glucose values." (PMID 25954817, 2015). "In a recent study of non-pregnant women with a history of gestational diabetes, a weak correlation was observed between MMP-8 and CRP, indicating that MMP-8 may be involved in modulating inflammation." (PMID 32923723, 2020).
injury (59 papers, 2012 to 2026). Damage inflicted on the body as the direct or indirect result of an external force, with or without disruption of structural continuity. "We conclude that the response (pro-inflammatory or otherwise) associated with early brain injury (as indicated by day 1 CRP) was prolonged such that (a) it was related to day 28 fatigue and (b) this relationship persisted at one month." (PMID 40746967, 2025). "As periprocedural elevation in CRP is associated with increased kidney injury, it was shown that CRPv was independently associated with kidney injury and patients with CRP velocity above 0.8 mg/L/h having a fourfold higher risk for AKI (15.2% vs. 3.8%, p < 0.01)." (PMID 35897672, 2022). "However, some studies have pointed out that CRP may play a protective role in alveolitis, and in patients with acute lung injury, an increase in CRP levels is associated with a decrease in mortality." (PMID 37990060, 2023). "The robust inflammatory response in the acute stage of abdominal trauma in patients with a daily caloric intake of <50% of resting energy expenditure was reflected by higher CRP and PCT levels." (PMID 37324740, 2023). "In the current investigation, we also discovered that infection-related markers, for instance, PCT, CRP, and leukocyte count were considerably higher in individuals who had suffered heart injury." (PMID 36505005, 2022). "In contrast, only elevated neutrophils count (P = 0.0007); CRP (P<0.0001); serum ferritin (P<0.0001) and LDH levels (P<0.0001) showed a significant association with acute liver injury." (PMID 34855832, 2021). "Profile of total protein plasma and C-reactive protein in rat models with acute skin injury infected with methicillin-resistant Staphylococcus aureus." (PMID 34566324, 2021). "Both CRP at time of early brain injury (reflected by the day 1 assay) and on day 28 were associated with fatigue, but not CRP at time of delayed brain injury or complications related to hospitalisation (on day 7), contrary to previous studies." (PMID 40746967, 2025). "The lack of correlation between suPAR and clinical infection status in this cohort, as well as with CRP values, indicates that suPAR elevation in post-acute brain injury is more likely reflective of the neuroinflammatory response rather than secondary infectious complications." (PMID 39540961, 2024). "The clinical efficacy was evaluated by the visual analog scale (VAS), American Spinal Injury Association (ASIA) scale, erythrocyte sedimentation rate (ESR), C-reactive protein (CRP), kyphotic angle, correction rate of kyphosis, angle loss, and bone graft fusion time." (PMID 36419079, 2022). "Previous reports demonstrated that serum NGAL is closely correlated with sCr, eGFR, and CRP and could thus serve as a marker of chronic impaired kidney function/kidney injury." (PMID 34830685, 2021). "Clinical outcomes including demographic characteristics, erythrocyte sedimentation rate (ESR), C‐reactive protein (CRP), visual analog scale (VAS), the Oswestry Disability Index (ODI), American Spinal Injury Association neurological classification, and lordotic angle were analyzed." (PMID 32524753, 2020). "Bone trauma led to higher CRP levels than fat and soft-tissue damage after TKA and THA." (PMID 33266181, 2020). "However, C-Reactive Protein (CRP) Test was significantly higher in the group with liver injury (P=0.01, respectively)." (PMID 33425269, 2020). "In head-injured children, serum IL-6 and CRP levels are elevated and correlated to the severity of head trauma and increased levels of IL-6 in the early phase of severe acute traumatic brain injury is associated with the high inflammatory response such as development of ARDS." (PMID 31805967, 2019).
injury (continued). "The lumbosacral angle, visual analogue scale (VAS) score, erythrocyte sedimentation rate (ESR), C-reactive protein (CRP) level, American Spinal Injury Association (ASIA) grade and Social Functioning-36 (SF-36) score were determined to ascertain the clinical effects of the treatment." (PMID 29202743, 2017). "However, another study indicates that, although the levels of CRP are elevated in patients with acute lung injury, a higher level of plasma CRP predicts a more favorable outcome in adult patients." (PMID 26257731, 2015). "At admission, the median level of PCT was consistent with the severity of brain injury as follows: mild 0.08 ng/ml (0.05 - 0.13), moderate 0.25 ng/ml (0.11 - 0.55) and severe 0.31 ng/ml (0.17 - 0.79), but the range of CRP levels varied greatly within the given severity of brain injury." (PMID 24330775, 2013). "Moreover, neuroprotective features of targeting CRP may be beneficial in the setting of severe trauma, especially when including a traumatic brain injury." (PMID 39773175, 2025). "In patients with CTCAE grade of >2, CRP at baseline (odds ratio [OR], 1.170; 95% confidence interval [CI], 1.06–1.30; P = 0.003), intubation (OR, 11.5; 95% CI, 2.31–57.3; P = 0.003), and GS (OR, 6.530; 95% CI, 1.25–34.0; P = 0.026) were independent factors of liver injury." (PMID 33147270, 2020). "The SHAP values indicated that CRP, BMI, neutrophil count, calcium levels, lactate, and NAR were the most significant predictors of acute lung injury." (PMID 40873797, 2025). "Macrophage-derived cytokines (ROS, IL) and inflammatory factors such as C-reactive protein (CRP), IL-6, IL-1 β, TNF- α and matrix metalloproteinase-9 (MMP9) after brain injury are related to renal injury." (PMID 35720359, 2022). "This study aimed to evaluate the prognostic value of key inflammatory and metabolic biomarkers: platelet-to-lymphocyte ratio (PLR), C-reactive protein-to-albumin ratio (CAR), serum lactate, base deficit, and neutrophil-to-lymphocyte ratio (NLR) in relation to ICU mortality in trauma patients." (PMID 41010921, 2025). "It is possible that CRP is not acting as a biomarker of inflammation, but something else, for instance the hepatic acute phase response to early brain injury." (PMID 40746967, 2025). "Correlations between ΔAlb0-72h and CRP, Bilirubin and AFOS at 72 hours also suggest that inflammation and cholestatic liver injury may play a role in the rate of decrease of P-Alb in cardiogenic shock." (PMID 31095609, 2019). "What’s more, inflammation-related factors including CRP, ICAM-2, and MMP-9 were also elevated, suggesting that after traumatic brain injury, the innate immune system was activated, then the inflammatory factors damaged the blood–brain barrier and were released into the blood." (PMID 30766469, 2018). "We demonstrate a role for TGF-β and M-CSF, but not CRP in generating these cells using monocytes from healthy volunteers incubated with plasma from trauma patients." (PMID 23285029, 2012). "White blood cell (WBC), Neutrophil, Ferritin, D-dimer, Troponin, CRP, SII, interleukin-6 IL-6, AST, ALT and LDH levels were higher in patients with liver injury compared to pregnant women without liver injury." (PMID 38356834, 2024).
pericardial effusion (59 papers, 2016 to 2026). Fluid collection within the pericardial sac, usually due to inflammation. "Nomogram included independent risk factors of age, c-reactive protein, centric pulmonary carcinoma, and pericardial effusion." (PMID 37519821, 2023). "Multivariate logistic regression analysis showed that age, c-reactive protein, centric pulmonary carcinoma, and pericardial effusion were independent risk factors, the last two of which were important independent risk factors as confirmed by PSM analysis." (PMID 37519821, 2023). "We found that increased values in cardiac enzymes (myoglobin, CK, CK-MB), LDH, platelets, and CRP were associated with the presence of pericardial effusion, with myoglobin showing the highest correlation index." (PMID 36013560, 2022). "Laboratory investigations revealed an elevated C-reactive protein and erythrocyte sedimentation rate, and echocardiography showed a small amount of pericardial effusion associated with multiple pericardial caseous masses (up to approximately 2.4 cm × 6.9 cm) without pericardial constriction." (PMID 40371065, 2025). "Moreover, the patient’s CRP levels were constantly within normal range and the poor response to corticosteroids should have suggested a cause for the relapsing pericardial effusion other than SLE, as lupus serositis tends to increase both CRP and ESR levels." (PMID 28351431, 2017). "Chronic immune activation and a persistent inflammatory state, with increased blood levels of the inflammatory cytokines–TNFα, IL-6, and CRP, associated with a direct cardiac involvement may induce pericardial effusions, with a lower occurrence among patients under antiretroviral therapy." (PMID 36013560, 2022). "Several AEs previously undocumented in drug labels were identified, including pericardial effusion, elevated C-reactive protein, hemolytic anemia, hemoptysis, and decreased hemoglobin." (PMID 40137538, 2025). "As the recurrences were always characterised by an overt inflammatory phenotype (characterised by fever, increased C-reactive protein, and pericardial effusion), we administered off-label tocilizumab (an IL-6 receptor antagonist) as a last treatment option." (PMID 41210896, 2025). "Those with detectable cTnI exhibited more severe functional class symptoms, a reduced six-minute walk distance, increased pericardial effusions, an enlarged right atrial area, and elevated B-type natriuretic peptide and C-reactive protein levels." (PMID 39451452, 2024). "She showed severe pericardial effusion with partial signs of hemodynamic compromise, while laboratory tests showed increased CRP (299 mg/L) and WBC (20.63 × 109/L)." (PMID 39458001, 2024). "Pleural and/or pericardial effusion along with elevated inflammatory markers, such as C-reactive protein (CRP) and erythrocyte sedimentation ratio, are common findings." (PMID 39421078, 2024). "The independent predictors for NOAF by multiple regression analysis were age, c-reactive protein level, centric pulmonary carcinoma and pericardial effusion (all P < 0.05)." (PMID 37519821, 2023). "The total point was calculated with age, c-reactive protein level, centric pulmonary carcinoma, and pericardial effusion." (PMID 37519821, 2023). "Based on the results of multivariate analysis, independent risk factors for NOAF were incorporated in a nomogram model to predict NOAF, including age, c-reactive protein level, centric pulmonary carcinoma, and pericardial effusion." (PMID 37519821, 2023). "Nevertheless, proper biochemical monitoring including hs-cTn and CRP should also be performed for every patient with pericardial effusion in the post-acute phase of COVID-19 infection." (PMID 36676627, 2022). "The integrated approach for diagnosing post-MI pericarditis (PMIP), which combines the CMR findings of LPE together with either elevated CRP levels and/or the presence of pericardial effusion, demonstrates that 78 patients (41.7%) had PMIP." (PMID 35282340, 2022).